RN7SL740P (RNA, 7SL, cytoplasmic 740, pseudogene)
Gene: Miscellaneous RNA gene on chromosome 21 (33,918,995 to 33,919,338, reverse strand). Ensembl gene ENSG00000244294.
Homologues: Orthologues: chimpanzee Metazoa_SRP (98% identical), macaque Metazoa_SRP (70% identical). Paralogues in human: RN7SL33P (69% identical), RN7SL1 (67% identical), RN7SL2 (67% identical), RN7SL448P (65% identical), RN7SL3 (65% identical), RN7SL712P (65% identical), RN7SL714P (65% identical), RN7SL296P (64% identical), RN7SL45P (64% identical), RN7SL125P (64% identical), RN7SL664P (64% identical), RN7SL748P (64% identical), and 699 more.